BEST1 (bestrophin 1)
Diseases named in the same sentence as BEST1 in open-access papers (continued):
Sharing a sentence is not in itself a finding about the gene and the disease.
retinal degeneration (12 papers, 2010 to 2024). Degeneration of the retina. "Recent advancements in genetic analyses have revealed that mutations in some genes that are expressed in RPE, such as MERTK, RPE65, LRAT, or BEST1, cause retinal degeneration." (PMID 35504937, 2022). "Bestrophin 1 (BEST1) is an integral membrane protein that functions as a calcium-activated chloride channel in which mutations are known to cause retinal degeneration." (PMID 30572641, 2018). "Despite the discovery of the gene BEST1 in 1998, the mechanisms of pathogenesis underlying retinal degeneration by the BEST1 mutations remain unknown." (PMID 31216630, 2019). "Since L-type channels of the RPE regulate cell functions such as secretion or phagocytosis, the understanding of bestrophin-1 and Ca2+ channel interaction would then help to understand mechanisms of retinal degeneration." (PMID 21559412, 2011).
Stargardt disease (8 papers, 2013 to 2026). "Mutations include ABCA4 and BEST1 genes, which are found in different conditions such as Stargardt disease, Best disease, and also in age-related maculopathies." (PMID 40062075, 2025). "In this report, we described the case of a mother and daughter presenting with BVMD phenocopying Stargardt disease caused by a heterozygous pathogenic variant in BEST1." (PMID 36264634, 2022). "Variants in BEST1 have been frequently suggested to also be responsible for a Stargardt disease–like degeneration, owing to a shared pathophysiology." (PMID 36264634, 2022). "Here, we describe affected members of a 2-generation family with a Stargardt disease–like phenotype caused by a 2–base pair deletion insertion, c.1014_1015delGAinsCT;p.(Trp338_Asn339delinsCysTyr), in BEST1." (PMID 36264634, 2022). "Mutations in ABCA4 and BEST1 genes were found in Stargardt disease (STGD)." (PMID 40062075, 2025). "In this study, we employed hiPSCs derived from patients with Stargardt disease or Best disease, carrying pathogenic variants in ABCA4 or BEST1, respectively, to explore gene editing in human models." (PMID 41827889, 2026). "Mutations in Bestrophin-1 (BEST1) and Crumbs homolog 1 (CRB1) genes have also been reported in patients with Stargardt’s disease with wildtype ABCA4 gene." (PMID 40725253, 2025). "Caused by BEST1 (aka VMD2) mutations, this juvenile-onset macular degeneration, characterized by an abnormal RPE-photoreceptor interface and depressed EOG light peak, results in poor vision evident during the later stages of the disease." (PMID 24143172, 2013). "The most important differential diagnoses of atrophic late AMD are the gene ABCA4, PRPH2, and BEST1 inherited macular dystrophies, including Stargardt disease (STGD1), Best disease (BD), or pseudo-Stargardt multifocal pattern dystrophy (PSPD) in late atrophic stages." (PMID 38132220, 2023). "It is of note that Lumacaftor has been shown to rescue the processing and cell surface expression of ABCA4 mutants associated with Stargardt Disease; however, by western blot we previously found that it did not increase the expression of mutant Best1." (PMID 37110551, 2023).
macular degeneration (7 papers, 2007 to 2020). Loss of vision in the central portion of the retina (macula), secondary to retinal degeneration. "The family of bestrophin proteins (BEST1-4) was identified by linkage analysis to hereditary macular degenerations caused by mutations in BEST1." (PMID 30628889, 2019). "Mutations in the gene for bestrophin-1, BEST1, lead to different types of retinal or macular degenerations." (PMID 21559412, 2011). "Leber congenital amaurosis and macular degeneration were enriched in C0, which specifically expressed RPE65, OTX2, LRAT, and BEST1." (PMID 33072724, 2020). "The absence of functional defects in ocular tissue of Best1-modified mice, even in mutant mice up to 21 months of age, may be viewed in a more general debate of whether the nocturnal mouse is in fact a relevant model for macular degeneration in diurnal human." (PMID 31201163, 2019).
nanophthalmos (7 papers, 2011 to 2025). "We have defined the diagnostic yield of sequencing the coding variants in PRSS56, MFRP, TMEM98, MYRF, CRB1, and BEST1 in a large cohort of patients with nanophthalmos and high hyperopia." (PMID 33203948, 2020). "Two additional genes, CRB1 and BEST1 (VMD2), have been implicated in nanophthalmos and have profound roles in photoreceptor and retinal pigment epithelial (RPE) function, respectively." (PMID 29862063, 2018). "Furthermore, observation of normal Arden ratios on the EOG in the nanophthalmos individual suggest an alternative to BEST1 as the cause of disease, as individuals carrying pathogenic mutations in BEST1-associated nanophthalmos have an abnormal EOG Arden ratio." (PMID 31048900, 2019). "Here, we report a patient suffering from microphthalmia, microcornea, CC (OMIM 601547), and BVMD caused by novel heterozygous variants in BEST1 and CRYBB2 (OMIM 123620)." (PMID 37076855, 2023). "While six genes have been implicated in this hereditary condition (MFRP, PRSS56, MYRF, TMEM98, CRB1,VMD2/BEST1), the relative contribution of these to nanophthalmos or to less severe high hyperopia (≥ + 5.50 spherical equivalent) has not been fully elucidated." (PMID 33203948, 2020). "To date, five genes (i.e., MFRP, TMEM98, PRSS56, BEST1, and CRB1) and two loci have been implicated in familial forms of nanophthalmos." (PMID 29862063, 2018). "The risk of this second vision-threatening pathology, particularly angle closure glaucoma, may be higher than that of the general population (1.1%) in some IRD genotypes (e.g., BEST1, CRB1, MFRP) associated with microphthalmia/nanophthalmos." (PMID 41465105, 2025). "Thus far, genes identified in Mendelian cases of nanophthalmos have different roles in the retina (PRSS56, CRB1) and the retinal pigment epithelium (BEST1/VMD2, MFRP)." (PMID 31048900, 2019). "Although linkage in both families formally excluded the known nanophthalmos causal gene MFRP, we sequenced the protein-coding regions of that gene as well as BEST1 in one patient from each family, but detected no interesting variants in either gene (data not shown)." (PMID 21850159, 2011).
angle-closure glaucoma (6 papers, 2010 to 2025). The sudden increase of intraocular pressure, resulting in pain and an abrupt decrease in visual acuity. "We present a 47-year-old male patient with BRVO who was diagnosed with angle-closure glaucoma and a homozygous mutation of c.140G > A (p.R47H) in BEST1." (PMID 35768830, 2022). "Here, we present a case of angle-closure glaucoma (ACG) associated with a BEST1 homozygous mutation of ARB and a combined branch retina vein occlusion (BRVO) and analyze the correlation of these diseases." (PMID 35768830, 2022). "Herein, we describe the clinical and genetic characteristics of a young male diagnosed with ARB associated with angle-closure glaucoma resulting from a novel homozygous mutation in BEST1." (PMID 24859690, 2014). "Trabeculectomy has been regarded as a mainstay of initial treatment in eyes of angle closure glaucoma (ACG) with peripheral anterior synechia > 180° in the Chinese population while its efficacy in secondary ACG with BEST1 gene mutation remains unclear." (PMID 28056057, 2017). "In the light of our current finding that ARB is frequently associated with angle-closure glaucoma and that BEST1 mutations cause the developmental ocular disorder ADVIRC, we believe the role of BEST1 in ocular development and glaucoma merits further investigation." (PMID 21203346, 2010).
Rod-cone dystrophy (6 papers, 2014 to 2023). An inherited retinal disease subtype in which the rod photoreceptors appear to be more severely affected than the cone photoreceptors. "Case ID 24718 (Cone-rod dystrophy, autosomal recessive): A homozygous missense mutation in BEST1 was identified in the affected index patient (24718) and his affected brother (24719): NM_001139443.1:c.242G>A:p.Arg81His." (PMID 27391102, 2016).
age-related macular degeneration (5 papers, 2017 to 2025). Age-related loss of vision in the central portion of the retina (macula), secondary to retinal degeneration. "The authors screened for BEST1 mutation in patients with age-related macular degeneration (AMD) and other maculopathies and concluded that BEST1 mutations could cause various disease phenotypes." (PMID 28831140, 2017).
glaucoma (5 papers, 2010 to 2025). Increased pressure in the eyeball due to obstruction of the outflow of aqueous humor. "Details of glaucoma medications were not available but only two patients (BEST1, COL2A1) required surgical management (tube shunt)." (PMID 41465105, 2025).
Microcornea (5 papers, 2014 to 2024). A congenital abnormality of the cornea in which the cornea and the anterior segment of the eye are smaller than normal. "Alterations in BEST1 have been implicated in a spectrum of impaired ocular development, including reports of nanophthalmus, microcornea, early-onset cataract, and posterior staphyloma." (PMID 38278445, 2024).
retinoschisis (4 papers, 2021 to 2022). An inherited or acquired disorder characterized by splitting of the retina into two layers. "There is a report of a novel mutation in the BEST1 gene in two patients with retinoschisis-like changes, while no mutation was detected in the XLR gene." (PMID 34012682, 2021).
epilepsy (3 papers, 2013 to 2023). A brain disorder characterized by episodes of abnormally increased neuronal discharge resulting in transient episodes of sensory or motor neurological dysfunction, or psychic dysfunction. "As for Best1, the question is whether enhanced calcium signals in astrocytes directly affect Best1's function in epilepsy models." (PMID 23964202, 2013). "Recent studies provided evidence that reactive astrocytes in epilepsy and other CNS pathologies release GABA through Best1 anion channels." (PMID 33391173, 2020).
hyperopia (3 papers, 2017 to 2025). A refractive error in which rays of light entering the eye parallel to the optic axis are brought to a focus behind the retina, as a result of the eyeball being too short from front to back. "Hyperopia is common in some IRDs including AD BEST1-retinopathy, RS1 and some LCA genotypes (in the current cohort: AIPL1, ALMS1, CEP290, CRB1, CRX, TULP1)." (PMID 41465105, 2025). "Several genes (e.g., BEST1, CRB1, MFRP, PRSS56 and TMEM98) which have roles in both foetal ocular development and post-natal outer retinal maintenance, can be associated with high hyperopia and short axial length." (PMID 41465105, 2025). "Interestingly, (high) hyperopia (MFRP, MYO7A, BEST1) was more common in this group than myopia." (PMID 41465105, 2025).
Alzheimer disease (2 papers, 2017 to 2020). A progressive, neurodegenerative disease characterized by loss of function and death of nerve cells in several areas of the brain leading to loss of cognitive function such as memory and language. "We have previously reported that Best1 is expressed in hippocampal astrocytes at the distal peri-synaptic regions, called microdomains, right next to synaptic junctions, and that it disappears from the microdomains in Alzheimer’s disease mouse model." (PMID 29121962, 2017). "In a mouse model of Alzheimer’s disease (AD), astrocytes release excessive GABA through the Best1 channel." (PMID 32665584, 2020).
Atrophy (2 papers, 2020 to 2021). Any weakening or degeneration, especially through lack of use. "Pathogenic variants of BEST1 result in functional disorder of the RPE, with resultant accumulation of fluid, bis-retinoid N-retinyl-N-retinylidene ethanolamine (A2E), and lipofuscin, which subsequently lead to RPE atrophy and photoreceptor cell loss." (PMID 34012682, 2021).
breast carcinoma (2 papers, 2020 to 2022). "Studies show that bestrophin-1 is implicated in tumor suppression by a proapoptotic mechanism in breast cancer." (PMID 35646664, 2022). "A switch from hypermethylation in hyperplasia to hypomethylation and potential activation of BEST1 in invasive cancer could have a notable impact on nutrient uptake and cellular response, allowing breast cancer cells heightened capacity to grow and proliferate." (PMID 32051475, 2020).
glioma (2 papers, 2022 to 2025). A benign or malignant brain and spinal cord tumor that arises from glial cells (astrocytes, oligodendrocytes, ependymal cells). "BEST1 participates in glioma proliferation by regulating synaptic plasticity, potentially enhancing neuronal signal reception and tumour cell proliferation through synaptic remodelling." (PMID 41249152, 2025). "Bestrophin-1 may contribute to volume regulation in particular cell types, including glioma cells." (PMID 35646664, 2022).
Leber hereditary optic neuropathy (2 papers, 2020). Leber's hereditary optic neuropathy (LHON) is a mitochondrial neurodegenerative disease affecting the optic nerve and often characterized by sudden vision loss in young adult carriers. "In the pediatric cohort, 78.8% of families showed causative variants in autosomal genes (most frequently ABCA4 and BEST1), 20.7% in X-linked genes (most commonly RS1 and RPGR), and 0.5% in mitochondrial genes (associated with Leber hereditary optic neuropathy)." (PMID 32423767, 2020).
virus infection (2 papers, 2018 to 2019). "For electrophysiological analysis, we first utilized iPSC-RPE carrying the BEST1 R218H mutation to optimize the time course and MOI of virus infection, as R218H is a null mutation with normal membrane localization of endogenous BEST1, representing a “clean” case with strong phenotypes." (PMID 31836750, 2019).
autosomal recessive retinitis pigmentosa (1 paper, 2011). Autosomal recessive retinitis pigmentosa (RP) is an autosomally recessive inherited retinal dystrophy leading to progressive loss of the photoreceptors and retinal pigment epithelium and resulting in blindness usually after several decades. "Indeed, mutations in the BEST1 gene have been found not only in patients with BVMD but also in patients with ARB and AVMD as well as in patients affected by autosomal dominant or autosomal recessive retinitis pigmentosa." (PMID 21293734, 2011).
Blindness (1 paper, 2017). Blindness is the condition of lacking visual perception defined as a profound reduction in visual perception. "Mutations in the human BEST1 gene lead to retinal degenerative diseases displaying progressive vision loss and even blindness." (PMID 29063836, 2017).
colon cancer (1 paper, 2020). "The upregulation of BEST1 in colon cancer cells has been shown to significantly increase cell growth, indicating BEST1 as an essential accelerator of cell proliferation." (PMID 32051475, 2020).
colorectal cancer (1 paper, 2023). A primary or metastatic malignant neoplasm that affects the colon or rectum. "Intriguingly, in addition to HNSCC, the lung, breast, and colorectal cancer, had consistently high levels of BEST1 expression on classical monocytes." (PMID 37088729, 2023).
head and neck squamous cell carcinoma (1 paper, 2025). A squamous cell carcinoma that arises from any of the following anatomic sites: lip and oral cavity, nasal cavity, paranasal sinuses, pharynx, larynx, and salivary glands. "In head and neck squamous cell carcinoma, VEGF-A promotes tumour proliferation by upregulating BEST1 expression in monocytes and enhancing the secretion of cytokines such as IL-6 and IL-8." (PMID 41249152, 2025).
invasive breast carcinoma (1 paper, 2020). A carcinoma that infiltrates the breast parenchyma. "While BEST1 is hypomethylated in invasive breast cancer compared to healthy breast tissue, it is hypermethylated in ADH and without any change in DCIS stage." (PMID 32051475, 2020).
macular coloboma (1 paper, 2022). "Moreover, variations in BEST1 and RIMS1 were reported in a Chinese patient with bilateral macular coloboma." (PMID 36429029, 2022).
macular holes (1 paper, 2025). A hole in the macula of the retina. "We report a case of retinal detachment and macular hole (MH) in a middle-aged patient with both ABCA4 and BEST1 mutations." (PMID 40062075, 2025).
multiple myeloma (1 paper, 2016). "The proteasome inhibitor bortezomib (BTZ, also known as Velcade) is currently in use for the treatment of multiple myeloma, and we tested whether this inhibitor was also able to restore expression levels of mutant bestrophin-1." (PMID 27519691, 2016).
refractive error (1 paper, 2025). A defect in the focusing of light on the retina as in astigmatism, myopia, or hyperopia. "Some genes implicated in IRDs (e.g., BEST1, LRP5, MFRP) affect organogenesis, modulating ocular development in the foetal and early childhood phases, leading to early-onset myopic or hyperopic refractive errors." (PMID 41465105, 2025).
Retinal atrophy (1 paper, 2017). A nonspecific term denoting wasting, especially as a result of degeneration, of the retinal pigment epithelium (RPE) and neurosensory retinal cells. "Patient 2, a 72-year-old otherwise healthy man, who has a homozygous c.602T > C; p.I201T mutation in BEST1, showed a dropped vision acuity at 20/40 in the right eye, and 20/200 in the left eye mainly due to aging-caused retinal atrophy." (PMID 29063836, 2017).
Stroke (1 paper, 2025). Sudden impairment of blood flow to a part of the brain due to occlusion or rupture of an artery to the brain. "Recent findings showed that stroke‐induced extrasynaptic glutamate release via BEST1 leads to delayed excitotoxicity in the mouse motor cortex, suggesting that BEST1 may play a role in modulating neuronal slow tonic neurotransmitter release in pathological conditions." (PMID 39466647, 2025).
tufting enteropathy (1 paper, 2024). "In the case of patient 6, however, the dual molecular diagnosis of homozygous pathogenic variants in EPCAM and BEST1 did not correspond to a hybrid phenotype because her only presentation was diarrhea as part of EPCAM-related tufting enteropathy (OMIM# 613217)." (PMID 38716412, 2024).